RAC1 (Rac family small GTPase 1)
Diseases named in the same sentence as RAC1 in open-access papers (continued):
Sharing a sentence is not in itself a finding about the gene and the disease.
tumor (continued). "In Fanconi Anemia (FA), there are gene mutations that are known to increase tumor invasion in HNSCC via the Rac1 GTPase, acting downstream of the DNA-PK pathway." (PMID 27597870, 2016). "In fact, plasma membrane/perinuclear Rac1 immunopositivity, which is closely linked to its active form 29, 30, was significantly lower in peripheral tumor lesions as compared to the core areas of GBMs." (PMID 27790861, 2016). "Rac1b interfered with Rac1 activation by PDGF, led to a reduction in membrane-bound Rac1, and promoted an increase in Rho activity which finally resulted in tumour-linked alterations in cell morphology and motility." (PMID 24378395, 2014). "Rac1, for example, is also involved in cell adhesion and migration and Rac1 activation is associated with increased tumor invasiveness, suggesting that Rac1 and downstream effectors are useful anticancer targets." (PMID 24040362, 2013). "Rac1b, a tumor associated and constitutively active Rac1 splice variant, is upregulated in colorectal tumor cell and can promote transformation of NIH3T3 cells." (PMID 23538840, 2013). "Taken together, these data suggest that Cdc42, Rac1 and RhoA are all closely associated with the invasion and metastasis of tumor cells through regulating the formation of invadopodia." (PMID 23538840, 2013). "CAF-secreted metalloproteases, such as MMP-3, elicit a Rac1b (a tumor-specific splice variant of Rac1)/COX-2-mediated release of ROS in carcinoma cells which is mandatory for EMT, stemness, and dissemination of metastatic cells." (PMID 21914164, 2011). "Deficiency of the Rac GEF Tiam1 in MMTV-Neu mice delayed tumor onset and decreased metastasis suggesting that Rac1 activity plays a causal role in MMTV-Neu induced tumor formation and progression." (PMID 20860838, 2010). "RhoA, Rac1, and Cdc42 have each been implicated in tumor motility and invasion, are downstream effectors of both LPA1 and S1P1, and therefore were candidates for targeting." (PMID 17156449, 2006). "Moreover, the associations between RAC1 alterations, efferocytosis activity, and tumor progression remain correlative and require further mechanistic experiments to establish causality and clarify the underlying biological pathways." (PMID 41498044, 2025). "In addition, RAC1 has been implicated in inducing tumour dormancy and conferring resistance to chemotherapies in environments characterised by a stiff matrix." (PMID 40715090, 2025). "However, bona fide tumor-associated activating mutations in RAC1 have been identified, with the RAC1P29S hotspot mutation associated with resistance to BRAF-targeted therapies." (PMID 39636745, 2025). "In addition, Rac1 is associated with tumor angiogenesis, the promotion of cell survival under endoplasmic reticulum stress, regulation of the survival of glucose-independent cells, and tumor drug resistance." (PMID 39673684, 2025). "Increased RAC1 expression was associated with tumor metastasis and the prognosis of LUAD patients." (PMID 40904408, 2025). "Single-cell transcriptome analysis identified RAC1 expression primarily in epithelial cells, associated with tumor progression, and spatial transcriptome analysis showed a mutually exclusive co-localization between B cell infiltration regions and RAC1-expressing epithelial cells." (PMID 39898257, 2025). "RhoGTPase Rac1 protein, primarily involved in cell adhesion and motility in migrating cells, has been implicated in oxidative stress, enhancing the production of ROS and, in particular, ROS-mediated tumor inflammation." (PMID 38362155, 2024). "Importantly, the overactivation and overexpression of Rac1 are closely associated with aggressive tumor growth." (PMID 39286779, 2024). "Thus, the association between RCC2 and Rac1 concerning apoptosis depends on more complex factors that ultimately influence the response of tumor cells to drug-induced apoptosis." (PMID 39118792, 2024).
tumor (continued). "Importantly, RAC1 is implicated in therapy resistance of tumor cells against both cytoablative and targeted treatments." (PMID 36599922, 2023). "In particular, Rac1 protein participates in the membrane protrusion formation, driving tumor cell migration and the formation of membrane ruffles, also implicated in the metastatic potential of tumor cells." (PMID 35884472, 2022). "The abnormal expression of Rac1 is also associated with tumor." (PMID 35847360, 2022). "In addition, several observations have indicated that constitutively active mutants of RHOA and RAC1 can cause tumor growth in nude mice." (PMID 35454871, 2022). "Rac1 inhibition produced these differential effects on normal cells and tumor cells, which could be related to the mutation of Rac1 in tumor cells." (PMID 35031595, 2022). "NSC23766, a Rac1 inhibitor that prevents the functions of Rac1 GEFs such as Tiam and Trio, is available in an in vitro experimental setting; thus, the detection of activated Rac1 in tumor tissues would be linked to an option of molecular therapy targeting activated Rac1." (PMID 35110666, 2022). "Based on these findings, we hypothesized that deletion of GCTB-OCs by denosumab might decrease the level of sFRP in tumor tissues, activate a cascade of Wnt-5a/Ror2/Rac1 signaling, and finally cause the osteoblastic differentiation of GCTB-SCs." (PMID 35927428, 2022). "Indeed, Rac1 is linked with tumor cell migration, while RhoA is associated with tumor growth and metastasis formation." (PMID 33671551, 2021). "In Ustilago maydis, the causal agent of common smut of corn, RAC1 and Cdc42 are required for tumor formation on maize seedlings." (PMID 33924947, 2021). "If a robust association can be established, the level of endogenous RAC1 activity in the tumor could constitute a potentially informative marker, predictive of tumor response to MEK inhibitors in the clinical setting." (PMID 34831012, 2021). "We demonstrated that an increase in RAC1 copy numbers could lead to increased tumor cell growth independently of the RAC1 (P34R) mutation." (PMID 34638434, 2021). "The overexpression of Rac1 was linked to aggressive growth and other malignant characteristics of tumours, and a high level of Rac1 could predict a poor prognosis in different types of cancer." (PMID 32457348, 2020). "Rac1 is a member of the Rho family of small G proteins that can regulate actin cytoskeleton remodeling and promote the formation of cell membrane synaptic structures linked to tumor cell invasion and migration." (PMID 32822124, 2020). "Loss of XIAP and cIAP1 leads to stabilization of Rac1 and promotes tumor migration." (PMID 31248165, 2019). "Therefore, we performed xenograft experiments using H1299 and H1975 Rac1 WT and KO cells to determine if loss of Rac signaling and macropinocytosis affects tumor formation." (PMID 30609754, 2019). "However, SaOS‐2 cells showed the most remarkable reduction of the active form of Rac‐1, underlining that the mesenchymal stromal compartment can strongly affect the tumour cell phenotype and thus the OS evolution." (PMID 29517849, 2018). "Furthermore, the mutation of TIPE2 in sites which binds to Rac1, reversed this inhibitory effect on tumor cell invasiveness." (PMID 30186591, 2018). "The small GTPase Rac1 has been implicated in the formation and dissemination of tumours." (PMID 26887924, 2016). "The possible intracellular cues that can direct this Endo180-associated tumor cell plasticity include Cdc42 and Rac1 and the Rho-ROCK-MLC2 pathway, which are activated by the spatiotemporal localization of the Endo180 receptor to the plasma membrane or constitutively recycling endosomes." (PMID 26567111, 2016). "This study supports that tumor-secreted vasoactive stimuli activate Rac1 to induce permeability and consequent transendothelial migration of tumor cells, and that loss of Rac1 function in endothelium is an effective therapeutic intervention for hematogenous metastasis." (PMID 25991673, 2015).
tumor (continued). "Moreover, Rac1 is also considered to be required as a downstream molecule of many tumor-associated growth factors and pro-inflammatory mediators that are critical for the progression and malignancy of tumor." (PMID 25991673, 2015). "Moreover, FAK has been linked to the invasive phenotype of tumours in a kinase and Rac1-dependent manner." (PMID 23681745, 2013). "Perturbation of Cdc42, Rac1 and RhoA activity results in the loss of normal physiological function and can be related to the pathological conditions, including cellular transformation, tumor invasion and metastasis." (PMID 23538840, 2013). "The recurrent mutation identified in seven of the tumor samples was a substitution of a proline for a serine at amino acid 29 in RAC1 (Ras-related C3 botulinum toxin substrate 1; RAC1P29S), a small Rho GTPase family protein with roles in proliferation, migration, and cytoskeletal rearrangements." (PMID 23372575, 2012). "Typically, migration and invasion of tumor cells is promoted by the loss of interaction of adherens junctions with the cytoskeleton and subsequent changes in the activities of Rho family small GTPases such as Rac1 and Cdc42." (PMID 23300597, 2012). "Furthermore, analysing 21 tumour samples as to the expression of the rac1 splice variant rac1b, we found that also rac1b mRNA is expressed at similar levels in all the tumours investigated (data not shown)." (PMID 12237774, 2002). "The increase in RhoA and Rac1 levels observed after mechanical stretching in clinical samples supports the hypothesis that these markers are closely associated with the mechanical environment of the tumor." (PMID 39887960, 2025). "Additionally, we found that tumor size (P=0.013), tumor’s anatomical location (P=0.031), N stage (P=0.002), clinical stage (P=0.035), and survival status (P<0.001) were significantly associated with the expression of Rac1." (PMID 38344200, 2024). "Rac1 protein could be used as an independent tumor diagnostic marker and survival predictor." (PMID 37434402, 2023). "Nuclear accumulation of RAC1 promotes nuclear plasticity, causing a loss of cytoplasmic active RAC1 with a concomitant increase in RhoA that drives actomyosin-mediated changes in cell morphology, the two attributes contribute to intensifying the aggressiveness of tumor cells." (PMID 35013128, 2022). "Therefore, trisomy of chromosome 7 and additional RAC1 copy numbers might have been the cause of tumor progression." (PMID 34638434, 2021). "In addition, we found that PAD2 depletion suppresses the expression of the cytoskeletal regulatory proteins RhoA, Rac1, and Cdc42 and also promotes a mesenchymal to epithelial-like transition in tumor cells with an associated increase in the cell adhesion marker, E-cadherin." (PMID 28549415, 2017). "However, since these embryos die at E9.5, before developmental angiogenesis can proceed fully, the precise effect of endothelial-Rac1-deficiency in tumor angiogenesis in vivo is unknown." (PMID 20339539, 2010). "Rac1, a small GTPase, is essential for actin cytoskeleton remodeling and macropinosome formation, facilitating nutrient scavenging in tumor cells." (PMID 40917745, 2025). "Considering potential targets of Rac1 signalling, we assessed the expression of snail, a master regulator of epithelial to mesenchymal transition (EMT) implicated in tumour aggressiveness." (PMID 40476337, 2025). "In small cell lung cancer, DOCK3 mediates tumor cell adhesion, migration, and invasion through activating the RAC1 signaling pathway." (PMID 41200217, 2025). "Collectively, these findings identify CAV1 as a central regulator of tumour dormancy-associated pathways and acquired TKI-resistance through modulation of E-cadherin, RAC1 and p21, alongside activation of the P70S6K and STAT3 pathways." (PMID 40715090, 2025). "Mechanistically, TIPE2 has the capacity to bind directly with RAC1, thereby suppressing its activity and, consequently, hindering tumor progression." (PMID 40904408, 2025).
tumor (continued). "RAC1 is an important member of the Rho GTPase family, and it participates in both cell proliferation and tumor metastasis." (PMID 40904408, 2025). "Our study provides critical mechanistic insights into the impact of RAC1A159V mutation on TIME and presents a potential approach for overcoming tumor immune evasion in the context of targeted inhibition of aberrant RAC1 signaling." (PMID 41160695, 2025). "Our data revealed the critical roles of miR-22 in inhibiting Rho, RAC1, RhoG, and RhoH GTPase cycles at the tumor margin or outside the tumors." (PMID 39953622, 2025). "In the single-cell data of LUAD and PAAD, the expression of RAC1 in tumour epithelial cells is significantly higher than that in normal epithelial cells." (PMID 39898257, 2025). "Results also supported that RAC1 is up-regulated in LUAD tumor tissues compared with normal tissues." (PMID 40904408, 2025). "Through the regulation of YAP1, TEAD4 binds to the TIAM1 enhancer region, thereby activates the expression of TIAM1 and subsequently increases the activity of RAC1 and induces the formation of invadopodia formation and promotes tumor metastasis." (PMID 40746611, 2025). "In the STAD single-cell data, although the expression of RAC1 on Mono/Macro cells in tumour tissue has increased compared to normal tissue, it can be observed that the increases is not as significant as the rise in epithelial cells." (PMID 39898257, 2025). "Rac1 therefore has a great deal of promise for improving immune response and tackling medical issues such as tumor treatment resistance." (PMID 41188920, 2025). "In particular, uPAR-integrin–mediated activation of Rac1/Cdc42 underlies the formation and maintenance of invadopodia, the actin-rich, membrane-based structures essential for ECM degradation and tumor cell invasion." (PMID 41154366, 2025). "We further analyzed the differences in RAC1 expression levels between paired tumor and normal tissues." (PMID 39898257, 2025). "Across the GSE175540 cohort, RAC1 expression exhibited marked variability among samples, with several tumor‐rich sections showing elevated transcript abundance." (PMID 41498044, 2025). "Tumor segmentation analysis confirmed significantly higher RAC1 expression in tumor core regions compared with peripheral areas across all four sections (all p < 0.001)." (PMID 41498044, 2025). "Rac1 plays a role in cell proliferation and migration and in tumor development, invasion, and metastasis formation." (PMID 40076757, 2025). "HACE1 blocks the generation of ROS by Rac1-dependent NADPH oxidases, thereby alleviating the initiation and progression of tumor cells caused by DNA oxidative damage and cyclin D1-driven hyperproliferation." (PMID 40948788, 2025). "The tumor cell phenotype mediated by the Wnt-β-catenin pathway of Rac1 GTPase signal transduction was found in triple-negative breast cancer." (PMID 39673684, 2025). "The rigidity of the tumor matrix controls downstream signals by inducing Rac1 and Rac1b, which play an important role in promoting EMT." (PMID 39673684, 2025). "This interaction abrogates the SENP1-dependent de-SUMOylation of Rac1, a prerequisite for activating Rac1, thereby facilitating tumor progression." (PMID 40400456, 2025). "RAC1 is now well recognized as an important player in tumor initiation, progression, and metastatic dissemination and is also involved in immune escape and resistance to anti-tumor therapies." (PMID 40633540, 2025). "TIPE3 is predominantly found in the cytoplasm and membrane of tumor cells, while RAC1 is primarily located in the cytoplasm of tumor cells." (PMID 40904408, 2025). "Flow cytometry analysis enabled the precise quantification of RhoA and Rac1 at the single‐cell level, offering a detailed, high‐resolution view of the cellular heterogeneity within tumor populations." (PMID 39887960, 2025). "Our findings highlight RAC1 as a pivotal gene linking efferocytosis activity with tumor progression, immune remodeling, and oncogenic signaling pathways." (PMID 41498044, 2025).
tumor (continued). "Taken together, HACE1 regulates cellular oxidative stress in a Rac1-dependent manner and is essential in organ development and tumor suppression." (PMID 40948788, 2025). "Its overexpression in BC has been reported to drive tumor cell proliferation, invasion, and metastasis via the Rac1/MAPK signaling pathway." (PMID 40496857, 2025). "Disruption of lipid rafts or blocking ERK/Rac1 signaling abolishes these effects, and in vivo tumor-bearing mouse models show elevated serum s-uPAR correlating with angiogenesis." (PMID 41154366, 2025). "In this study, we demonstrate that the tumor-derived RAC1A159V mutation, a recurrent GOF mutation in RAC1, creates an immunosuppressive TIME, facilitating tumor evasion from immune attack." (PMID 41160695, 2025). "Ras-related C3 botulinum toxin substrate 1 (RAC1) and the Ras homolog gene family, member A (RhoA) signaling are important for promoting invadopodia or ectosomes in tumor cells." (PMID 39773634, 2025). "In this study, we found that CNV amplification significantly increases RAC1 expression, suggesting its potential role as a driver gene in tumor progression and malignant phenotypes." (PMID 39898257, 2025). "DOCK3 was shown to promote invasion via RAC1 and is directly regulated by tumor-suppressive miRNAs such as miR-512-3p." (PMID 41200217, 2025). "To explore the role of RAC1 in the immune microenvironment, we collected single-cell sequencing data from paired normal and tumor tissues for BRCA14, LUAD15, PAAD17 and STAD16 from public databases, with BRCA also including paired metastatic lymph nodes." (PMID 39898257, 2025). "In recent times, the role of Rho GTPase Activating Protein17 (ARHGAP17) as a tumor suppressor and negative regulator for Cdc42 and Rac1 has been the subject of investigation by researchers." (PMID 40969409, 2025). "It promotes neuronal sprouting into the tumor microenvironment via pathways involving focal adhesion kinase (FAK) and Rho GTPases (Rac1, Cdc42), enhancing tumor growth and potentially contributing to cancer-related pain." (PMID 40243726, 2025). "In RCC, studies show that RAC1 expression is significantly elevated compared to adjacent normal kidney tissue and correlates with higher tumor infiltration and worse prognosis." (PMID 41498044, 2025). "KDM6A exerts its anti-tumor effects through the epigenetic activation of RHGDIB transcription, which suppresses Rac1—a key regulator of tumor cell motility, invasiveness, and metastasis." (PMID 40600050, 2025). "One of the downstream effectors of RAC1, mammalian target of rapamycin (mTOR), promotes tumor cell metabolism including glycolysis and lipid biosynthesis." (PMID 41160695, 2025). "The effects of HACE1 on ESCA cells through RAC1 were elucidated by applying the RAC1 inhibitor EHop-016 in a tumor-bearing nude mouse model." (PMID 38706891, 2024). "shG9a tumour cells transfected with a RAC1Q61L (a constitutively active RAC1) expressing vector restored the oncogenic phenotype, suggesting that RAC1 is a key downstream effector of G9a." (PMID 40396280, 2024). "Along with RhoC, also the Rho GTPase Rac1, has been reported to actively sustain the tumor cell invasive behaviour and to activate YAP." (PMID 39495612, 2024). "VAV2 (DBL family of proteins) is a ubiquitous guanine nucleotide exchange factor for the small GTPase RAC1 and extensively studied for its role in neurite outgrowth and branching and tumor cell invasion." (PMID 38127456, 2024). "Microscopic visualization of histological sections indicated that combined treatment with 1A-116 and 5-FU reduced liver and lung metastasis development in mice, suggesting a role for Rac1 in CRC tumor growth, resistance, and metastatic dissemination." (PMID 39513883, 2024).